HIF1A (hypoxia inducible factor 1 subunit alpha)
Diseases named in the same sentence as HIF1A in open-access papers (continued):
Sharing a sentence is not in itself a finding about the gene and the disease.
lung carcinoma (continued). "An increased expression of hypoxia-inducible factor-1α (HIF-1α) is correlated with poor prognosis in some cancers, such as lung cancer, gastric cancer and breast cancer." (PMID 25811359, 2015). "For example, cetuximab was more cytotoxic against hypoxic than well-oxygenated A431 lung cancer cells grown in vitro and it reduced the overexpression of hypoxia markers like HIF-1α, CA9 and VEGF." (PMID 26032726, 2015). "H1299 xenografts in nude mice and lung cancer tissues from patients were used for immunohistochemistry to detect the expression and distribution of HIF-1α, CXCR4 and SDF-1α." (PMID 25843954, 2015). "HIF-1α overexpression in lung tumor cells is associated with increased invasion capacity and metastasis, and HIF-1α serves as a biomarker of poor prognosis in human lung cancer." (PMID 26528854, 2015). "For example, overexpression of HIF1α increased the invasive capacity of human lung adenocarcinoma cells, while antisense oligonucleotide of HIF1α inhibited the proliferation of lung cancer cells both in vitro and in vivo." (PMID 24567056, 2014). "HIF1A was reported as a target of MIR17HG in lung cancer cells, but the specific role of miR-18a in the control of HIF1A expression and activity was not tested." (PMID 25069832, 2014). "The overexpression of HIF-1α has been detected in certain cancers such as gastric, breast and lung cancer." (PMID 25089613, 2014). "Few works studied VEGF-A and HIF-1α together in lung cancer, and similar studies on early stage are scarce." (PMID 26316946, 2014). "The HIF-1α/VEGF/PEDF pathway exists as a critical step in lung cancer angiogenesis and tumor metastasis." (PMID 23869238, 2013). "Our findings in vivo, therefore, both corroborate a possible mechanism for upregulated survivin expression in A549, and provide a basis to target the HIF-1α pathway as a lung cancer therapy." (PMID 23732337, 2013). "Our study confirmed that HIF-1α and survivin are co-overexpressed in the lung cancer cell line A549." (PMID 23732337, 2013). "It is possible that BBR inhibited HIF-1α protein accumulation in lung cancer cells, and then suppressed the expression of the related genes which are involved in tumor cell proliferation." (PMID 23869238, 2013). "As expected, both inhibitors reduced basal and hypoxia-induced HIF-1α levels in EPLC-272H lung carcinoma cells." (PMID 22347438, 2012). "In summary, our data show a HIF-1α-independent radiosensitization of normoxic and hypoxic H1339 lung cancer cells by Hsp90 inhibition." (PMID 22347438, 2012). "Topotecan (TPT), a drug that inhibits the synthesis of HIF-1α proteins, has been used in clinical trials in treating ovarian cancer and lung cancer." (PMID 22665973, 2012). "A truncated form of the voltage-dependent anion channel 1 (VDAC1) is induced by HIF-1α to promote cancer cell survival and correlates with chemotherapy resistance in lung cancer patients." (PMID 23241400, 2012). "All together these data suggest a role for NF-κB in lung cancer promotion in the Gprc5a-/- mice in response to bacterial induced inflammation through activation of the HIF-1α pathway and its downstream angiogenic signals." (PMID 22239913, 2012). "Herein, we describe the effects of the novel Hsp90 inhibitor NVP-AUY922 and 17-allylamino-17-demethoxygeldanamycin (17-AAG), as a control, on HIF-1α levels and radiosensitivity of lung carcinoma cells under normoxic and hypoxic conditions." (PMID 22347438, 2012). "In hypoxic lung cancer cells, hypoxia leads to increased expression of Notch1 through a HIF-1α–dependent induction of Notch1 mRNA." (PMID 22363487, 2012).
lung carcinoma (continued). "HIF1α upregulation is important in the survival and angiogenic activity of radioresistant lung cancer cells, a situation where Hsp90 inhibitor treatment suppresses the HIF1α/Hsp90 interaction and HIF1α expression." (PMID 27721330, 2011). "Many factors including EGFR, HIF-1A, AKT1 and RAF-1 are known to be regulated by Hsp90 and their abnormal expression level is often associated with lung cancers." (PMID 21283735, 2011). "We found significantly increased HIF1α protein expression in hypoxic lung cancer tumor and colon cancer tumor." (PMID 21812995, 2011). "The specific HIF-1α-siRNA expressing plasmid was constructed and used to knock-down HIF-1α expression in the lung cancer cell line A549 cells in our previous report." (PMID 20727156, 2010). "MMP1 is also known to be upregulated by hypoxia and HIF-1a in breast and lung cancer cells, and also by CXCR4 in Nk cells and prostate cancer cells." (PMID 20102637, 2010). "The expression of HIF-1α is related to differentiation, lymph node metastasis and clinical stage of lung cancer." (PMID 19245702, 2009). "Further investigation into the precise mechanisms controlling HIF1A‐mediated ferroptosis may reveal additional therapeutic targets to combat lung cancer and overcome treatment resistance." (PMID 39912781, 2025). "Importantly, decreased RNF20 levels correlate with increased expression of HIF1α and its target genes, suggesting HIF1α inhibition as a promising therapeutic approach for lung cancer patients with reduced RNF20 activity." (PMID 40436847, 2025). "In addition, HIF1α is regulated synergistically with IGF1R in lung cancer through glycolysis and glutamine metabolism, result of including cancer malignant." (PMID 40290443, 2025). "LW6 (1–10 μM) facilitates the degradation of HIF-1α and suppresses autophagy in lung cancer cells." (PMID 40004215, 2025). "Additionally, AK4 overexpression promotes lung cancer metastasis by enhancing hypoxia-inducible factor 1α (HIF-1α) stability and epithelial-to-mesenchymal transition (EMT) under hypoxia." (PMID 40593461, 2025). "Therefore, we sought to elucidate the regulatory effect of the HIF-1α/HSP70 pathway on lung cancer recurrence after incomplete RFA." (PMID 40313865, 2025). "Knockdown of ATAD2 inhibited lung cancer cell invasion and migration, reduced mtROS production, and decreased both the quantity and functional capacity of CSCs, suggesting that IH accelerates lung cancer progression by activating the HIF-1α/ATAD2 axis, regulating mtROS and CSC interactions." (PMID 41194928, 2025). "Our experiments demonstrated that HIF1α-mediated reprogramming plays a major role in mediating the phenotype elicited upon RNF20 loss, therefore, we next correlated RNF20 levels with the expression of HIF1α and HIF1α-dependent metabolic enzymes in lung cancer patients." (PMID 40436847, 2025). "YFJDT exerts anti‐tumor effects in lung cancer by downregulating HIF1A and promoting ferroptosis." (PMID 39912781, 2025). "In turn, COX2 activation is also known to enhance HIF-1α activity in breast and lung cancer." (PMID 38612478, 2024). "Likewise, elimination of HOIP also decreased HIF1α expression in NCI-H460 lung cancer cells, and mouse macrophages." (PMID 38272870, 2024). "Additionally, analyzing the TCGA dataset using cBioportal for cancer genomics showed a reverse correlation between PDLIM2 and HIF-1α in lung cancer." (PMID 38880883, 2024). "TNFAIP6 expression has been discovered to be elevated in HIF-1α-induced lung cancer cells." (PMID 38376551, 2024). "The results revealed that 6-alpha-diol exhibited the highest affinity for HIF1A, suggesting that HIF1A may be a suitable target for lung cancer treatment." (PMID 39113883, 2024). "Targeting HIF-1α (hypoxia-inducible factor 1-alpha) offers a promising strategy for lung cancer treatment, as the HIF-1α pathway plays a key role in tumor adaptation to low oxygen, angiogenesis, metabolic changes, and survival, all contributing to cancer progression." (PMID 39682234, 2024).
lung carcinoma (continued). "The expression of PDLIM2 and HIF-1α was reversely correlated in lung cancer patients." (PMID 38880883, 2024). "The ATM/HIF1α signaling is also demonstrated in lung cancer." (PMID 39519130, 2024). "Therefore, LUBAC exacerbates angiogenesis and growth of lung cancer, which are contingent largely on HIF1α." (PMID 38272870, 2024). "It is uncovered that TNFAIP6 expression is elevated in HIF-1α-induced lung cancer cells." (PMID 38376551, 2024). "Notably, a meta-analysis conducted on 17 NSCLC histological studies found that HIF-1α expression was significantly higher in lung cancer tissues compared with normal tissues and was more elevated in NSCLC patients than in small-cell lung cancer patients." (PMID 39858431, 2024). "In summary, these findings suggest that HIF-1α is negatively regulated by PDLIM2 in lung cancer." (PMID 38880883, 2024). "Interestingly, it was observed that HIF1A was downregulated in primary lung cancer but was upregulated in liver metastasis in CTCs and exosomes." (PMID 38877052, 2024). "Previously, IDF-11774 was identified as a HIF-1α inhibitor in colorectal and lung cancers." (PMID 38140111, 2023). "Additionally, recent evidence suggested that HIF-1α inhibition was able to alleviate tumor immunosuppression induced by hypoxia and sensitize tumor’s response to immunotherapy in lung cancer." (PMID 36845145, 2023). "Furthermore, compound 50 inhibited HIF-1α-regulated CD73 expression under hypoxia in A549 lung cancer cells." (PMID 37242466, 2023). "The increase in HIF-1α (S) in these patients suggest that it may be due to lung cancer as well as cancer-related MPE." (PMID 37841777, 2023). "The aim was to investigate whether SIRT3 affected lung cancer development under hypoxic conditions via regulating the ROS-FPR1/ HIF-1α axis." (PMID 37747648, 2023). "Indeed, increased protein levels of HIF-1α and HIF-2α are associated with poor prognosis and metastasis in a number of cancers, including lung cancer." (PMID 37830546, 2023). "Therefore, we focused on HIF-1α as a promising key player in IP-mediated lung cancer progression and tumor microenvironmental changes, and demonstrated that a HIF-1α inhibitor was effective against lung cancer with IP." (PMID 38012636, 2023). "Excitingly, previous studies reported that succinate could stabilize HIF-1a expression and promote lung cancer cell migration through the PI3K/AKT signaling pathway." (PMID 37749638, 2023). "Another study from our lab found that propofol might inhibit the biology of lung cancer cells through glucose metabolism and HIF-1α relevant pathway." (PMID 36207479, 2023). "Additionally, previous studies have reported that KDM3A can be negatively regulated by miR-449a in lung cancer and activated by the transcription factor of HIF-1α in multiple myeloma." (PMID 37305393, 2023). "We hypothesized that HIF-1 inhibitors may be a potential treatment for lung cancer with interstitial pneumonia, and AsA, which promotes HIF-1α degradation, may be an alternative therapeutic candidate." (PMID 38012636, 2023). "Hence, prospectively examining HIF-1α expression in more cases of human lung cancer with IP is required." (PMID 38012636, 2023). "Therefore, we sought to elucidate the regulatory effect of the HIF-1α/HSP70 pathway on lung cancer recurrence after incomplete radiofrequency ablation." (PMID 37948404, 2023). "We wonder if the expression of PRMT5 and HIF-1α was changed in lung cancer cells induced by CoCl2." (PMID 37400960, 2023). "Finally, we showed an increased amount of HIF-1α inside EVs from COPD subjects who have developed lung cancer." (PMID 37838700, 2023). "We explored whether SIRT3 affects the development of lung cancer by regulating the reactive oxygen species (ROS)-FPR1/HIF-1α axis under hypoxic conditions." (PMID 37747648, 2023). "Specifically, high HIF-1α expression has been found in many subtypes of lung cancer." (PMID 37948404, 2023).
lung carcinoma (continued). "Similarly, hypoxia-induced autophagy is reported to be involved in the radioresistance of human osteosarcoma and lung cancer cells by HIF-1α activation." (PMID 36551540, 2022). "HSP70 promotes SUMO of HIF‐1α and promotes lung cancer invasion and metastasis." (PMID 35928554, 2022). "LncRNA FAM83A-AS1 enhances the migration of lung cancer cells by upregulating HIF1A." (PMID 36230902, 2022). "Moreover, SU5416 and KRN633 are VEGFR tyrosine kinase inhibitors that reduce HIF-1α expression in various cancer cells (excluding lung cancer)." (PMID 36338690, 2022). "The expression of HIF-1α in lung CAFs was also negatively correlated with the survival time of lung cancer patients, which highlighted that the HIF-1α/SCD1 axis in fibroblasts might be an ideal candidate for predicting the progression of lung cancer." (PMID 36439884, 2022). "Besides, it is generally known that nicotine enhances cell proliferation in lung cancer through increasing HIF1α." (PMID 34696659, 2022). "Other studies also demonstrated that HIF-1α-induced autophagy could contribute to the cisplatin resistance of ovarian and lung cancer cells via the upregulation of Beclin-1 and LC3." (PMID 36551540, 2022). "In addition, we show that serum lactate levels are positively correlated with serum EV levels and Rab27a and HIF-1α protein levels in the tumor tissues of lung cancer patients." (PMID 36531060, 2022). "The expression of ASS1 can be inhibited by HIF1α in lung cancer cells and by promoter methylation." (PMID 35655758, 2022). "CircAGFG1 enhances the migration of lung cancer cells by upregulating HIF1A." (PMID 36230902, 2022). "Previous study showed that SIRT6 might act as antioncogenesis factor by inhibiting HIF-1α, an angiogenesis-promoting molecule, in lung cancer, and by inhibiting c-Myc gene and ribosome biosynthesis." (PMID 35136826, 2022). "A previous study suggested that MIF overexpression could promote the Warburg effect of lung cancer cells via the NF-κB/HIF-1α signaling pathway, thus contributing to the progression of lung cancer." (PMID 36091041, 2022). "Radiation exposure induces HIF-1α protein expression in pancreatic cancer and lung cancer." (PMID 36418890, 2022). "Using a model of lung cancer, acute hypoxia leads to the stabilization of HIF-1α, increasing microvascular permeability and allowing the retention of myeloid cells, thus establishing a pro-metastatic environment characterized by a decrease in endothelial cells (CD31+CD45−)." (PMID 35565420, 2022). "Here, we also provide an overview of HIF-1α and its principal regulatory mechanisms, briefly describe HIF-1α-targeted therapy in lung cancer, and summarize substances that may be used to target HIF-1α at the level of COPD-induced inflammation." (PMID 36338690, 2022). "Inhibition of circASXL1 blocks migration and HIF1A expression of lung cancer cells." (PMID 36230902, 2022). "Hence, the HIF-1α/SCD1 axis represents a potential therapeutic target for lung cancer management, along with other components of the lipid metabolism pathway." (PMID 36439884, 2022). "In addition, it was also found that lung cancer-related lncRNA1 (LCAL1) can induce aerobic glycolysis of lung cancer cells through the AMPK/HIF-1α axis and promote the rapid proliferation of lung cancer cells." (PMID 36124026, 2022). "The overexpression of HIF1A was found to predict poor survival in lung cancer." (PMID 36110188, 2022). "However, sevoflurane has also been reported to suppress hypoxia-induced growth and metastasis of lung cancer cells by inhibiting HIF-1α." (PMID 35559987, 2022). "In fact, the deficiency of HIF-1α decreases epithelial inflammation and avoids the induction of lung cancer, even in the presence or absence of COPD, in a murine model." (PMID 35565420, 2022). "Besides, HIF1α enhances cisplatin resistance in lung cancer by regulating Xeroderma pigmentosum complementation group A expression." (PMID 34696659, 2022).
lung carcinoma (continued). "Moreover, geraniol, a monoterpene natural product, promotes the autophagy of CoCl2-treated lung cancer cells through the HIF1A/Beclin-1 pathway." (PMID 36139919, 2022). "However, a bypass tract capable of activating HIF-1α in EGFR-mutant lung cancer during EGFR suppression was also reported to be related to EGFR-TKI resistance." (PMID 36612121, 2022). "Furthermore, MAC induces autophagy by increased AMPK/Hypoxia-inducible factor 1 alpha (HIF-1α) expression in lung cancer cells." (PMID 36499465, 2022). "LncRNA TSLNC8 triggers apoptosis of lung cancer cells by regulating HIF-1α (HIF1A) signaling." (PMID 36230902, 2022). "Moreover, we confirmed the positive relationship between NRP1, HIF-1α, and VE-cadherin expression in lung cancer tissues via the public GEPIA, UCSC, and CCLE databases." (PMID 33850110, 2021). "However, while it has been widely accepted that complex coding/noncoding gene regulatory networks take part in the hypoxia-associated tumor progression, it remains largely elusive how HIF-1α/lncRNA axes participate in the development of lung cancer." (PMID 33407675, 2021). "Restraint of the PRX1/NF-κB pathway contributes to an attenuation of HIF-1α levels in lung cancer." (PMID 34575983, 2021). "We also examined hypoxic status by immunostaining for HIF1α in lung cancer tissue sections." (PMID 34483138, 2021). "It has reported that chrysophanol has an anti-tumor role in the cell proliferation of lung cancer via mediating ROS/HIF-1a/VEGF signaling cascade; additionally, it also suppresses cell growth, migration, and reactive oxygen species generation in oral cancer cell lines." (PMID 33622177, 2021). "The higher expression of HIF1α in lung cancer tissues indicated that hypoxia might contribute to tumor progression in lung cancer." (PMID 34362882, 2021). "From the axis of miR-449a/KDM3A/HIF-1α, the molecular mechanism of lung cancer has been further comprehended, and this axis may alight the potentials to treat lung cancer." (PMID 34044859, 2021). "In lung cancer, Daxx inhibits lung metastasis by suppressing the HIF-1α/HDAC1/Slug pathway." (PMID 34359912, 2021). "A549 cells that had been transfected with the plasmids were injected into mice to study whether miR-449a/KDM3A/HIF-1α axis regulated lung cancer progression in vivo." (PMID 34044859, 2021). "We determined a low expression of miR-449a in lung cancer and further figured out that over-expressing miR-449a delayed while suppressing miR-449a accelerated lung cancer development in vitro and in vivo, which was related to its negative regulation on HIF-1α." (PMID 34044859, 2021). "Just as hypoxia can lead to PGE2 synthesis, an in vitro study using lung cancer cells showed that PGE2 can in turn induce HIF-1α which increases VEGF, suggesting that a vicious cycle of hypoxia and inflammation can be triggered in certain tumours, resulting in progressive disease." (PMID 34094895, 2021). "Interestingly, such CSC were preferentially observed in hypoxic areas, named niches, and both HIF-1α and HIF-2α were associated with induction and/or maintenance of CSCs across many cancer types including lung cancer." (PMID 34298636, 2021). "HIF-1α level presented the same trend in lung cancer cells in vitro." (PMID 34044859, 2021). "Serving as a hypoxic response gene, KDM3A could be mediated by hypoxia-inducible factor-1α (HIF-1α), the key gene in lung cancer under a hypoxic microenvironment." (PMID 34044859, 2021). "In conclusion, our study suggested that ropivacaine inhibited the expression of HIF-1α in H1299 and A549 lung cancer cells, hence reducing the expression of its downstream effectors VEGF and MMPs and decreasing the ability of lung cancer invasion and metastasis potential per se." (PMID 35280249, 2021). "Besides, previous data showed that HIF1A combined with the transcription factor of epithelial-to-mesenchymal transition, Snail, to mediate the development of lung cancer." (PMID 34838012, 2021).